IL32 (interleukin 32)
Diseases named in the same sentence as IL32 in open-access papers (continued):
Sharing a sentence is not in itself a finding about the gene and the disease.
cancer (continued). "Regardless of its pro- or anti-cancer functions, IL32 expression was shown to be enhanced by miR-205 expression as this microRNA was shown to bind to the IL32 promoter." (PMID 29922517, 2018). "Analysis of the same cell lines in Cancer Cell Line Encyclopedia (CCLE) showed a similar pattern of IL32 expression (data not shown)." (PMID 28966727, 2017). "To determine whether PCs regulated Src‐Akt signaling in cancer cells via IL32‐β5‐integrin paracrine signaling, we treated cancer cells with CM from PCs transfected IL32 targeting siRNA or siNSC in the presence/absence of TKI drugs." (PMID 39435643, 2024). "Nevertheless, transgene-induced intracellular expression of a particular IL-32 isoform may not accurately reflect its mechanistic role in human cancers, given that it may not be secreted." (PMID 32841222, 2020). "Our results also provide potentially new mechanistic insight into the role of IL-32, demonstrating that myeloid cells but not lymphocytes or cancer cells respond to IL-32 treatment by activating the MAPK/ERK pathway, suggesting its binding to a hitherto unidentified surface receptor." (PMID 32841222, 2020). "In our previous work, we discovered an IL-32–dependent pathway of DC differentiation, and we showed that recombinant IL-32γ (here after referred to as IL-32) induces human DC maturation and activation of CD8+ T cells in vitro, suggesting its therapeutic potential in cancer." (PMID 32841222, 2020). "Treatment of lymphocytes with IL-32 may induce the expression of different cytokines, including tumor necrosis factor (TNF)-α or IL-8, which have been found to be involved in multiple inflammatory processes and cancer progression." (PMID 25435980, 2015). "Furthermore, targeted reduction of IL-32 expression and, consequently, its secretion by T cells could favor patients suffering from diseases, in which T cells are the major IL-32 producers, like HIV-infection, beta cell autoimmunity and cancer." (PMID 39211051, 2024). "Like IL32, the expression of CCL8 was upregulated in the non-transformed tissue of right-sided cancers, which are known to be more aggressive." (PMID 34885960, 2021). "Although datasetA and datasetB were baseline nonmetastatic cancers that had not undergone ICI therapy, we still observed obvious similarities in spatial distribution patterns across ADGRE5, IL32 and STAT5A/B." (PMID 38343549, 2024).
infection (42 papers, 2008 to 2026). The state of being infected such as from the introduction of a foreign agent such as serum, vaccine, antigenic substance or organism. "Consistently, an in vitro infection model using PBMCs from healthy volunteers with macrophage-tropic HIV strains resulted in the upregulation of multiple variants of IL-32, including (α, β, γ, ε, θ) as well as IL-32D." (PMID 41383621, 2025). "The silencing of the gene encoding IL-32 in THP-1 macrophages infected with Leishmania led to an increase in infection." (PMID 37233274, 2023). "Expression of IL-32 has been associated with the severity of inflammation in rheumatoid arthritis and the control of infection with Mycobacterium tuberculosis and M. bovis as well as the pathogenesis of chronic hepatitis B." (PMID 35097133, 2022). "Interleukin-32 is a novel inflammatory mediator that has been described to be important in the immunopathogenesis and control of infections caused by Leishmania parasites." (PMID 32023240, 2020). "In fact, IL-32 has also been implicated as a key player in controlling parasite load in infections caused by L. braziliensis or L. amazonensis in both the IL-32γ-transgenic mouse model and human cells." (PMID 32023240, 2020). "During infection caused by influenza A virus, human immunodeficiency virus or Mycobacterium avium an increase of IL-32 production has been reported." (PMID 24884781, 2014). "To investigate a possible association between severity of lung injury and SNPs, we analyzed the number of ventilator-free days (VFDs) associated with each IL-32 SNP for patients with infection-associated ALI." (PMID 21649914, 2011). "The presence of this IL32 variant was also associated with a decreased infection index." (PMID 35309341, 2022). "In addition to the role of IL-32 in the production of microbicidal molecules we observed that after 4 h of infection the percentage of infected macrophages was inversely associated with IL-32 expression." (PMID 28241012, 2017). "Therefore, the ability of M. leprae MDP to induce both IL-32 and CD1b+ DC is linked to host defense at the site of infection." (PMID 27297389, 2016). "Conversely, the KLRB1+ cluster (cytokine-producing cluster), enriched for cytokine/chemokine genes (CCL5, IFNG, IL32), were depleted during infection." (PMID 41544143, 2026). "In response to influenza virus infection, serum IL-32 levels were significantly elevated, and the infection of lung epithelial cells resulted in a substantial increase in IL-32 release into the supernatant." (PMID 40149726, 2025). "For example, miR-29b can directly target the 3’-UTR of IL-32 and reduce its level through acceleration of IL-32 mRNA degradation in HepG2 and Huh7 cells on infection with the hepatitis B virus." (PMID 41383621, 2025). "Increased IL-32 expression has been found in hepatocytes of patients suffering from chronic HBV or HCV infection." (PMID 37686029, 2023). "The expression of IL-32 is upregulated by several cytokines, including TNF and IL-1β, as well as by infection, pathogen-associated molecular patterns (PAMPs) and oxidative stress." (PMID 37686029, 2023). "Infection with Leishmania amazonensis induced high IL-32 expression which enhanced the immune response against the pathogen and supported healing of skin lesions." (PMID 37727785, 2023). "Infection with T. cruzi reduced the amount of IL-32 in the cardiac tissue after 15 days, but after 28 days, the levels were recovered to the levels of noninfected mice." (PMID 35097133, 2022). "In IL-32γTg, infection with T. cruzi significantly decreased IL-32 production in situ at 14 days postinfection." (PMID 35097133, 2022). "In this context, the role of IL-32 was investigated in infection with Leishmania sp., which indicated IL-32 as a crucial player in the immune responses against this parasite." (PMID 35309341, 2022). "In this study, we described how IL-32 isoforms are crucial to host defense against new world Leishmania species infections." (PMID 32023240, 2020).
infection (continued). "Infection of human macrophages or PBMCs with M. tuberculosis H37Rv induced IL-32 production, suggesting a role for IL-32 in the control of M. tuberculosis infection." (PMID 30426023, 2018). "In the present study, silencing and overexpression of IL-32 was performed in THP-1-derived macrophages infected with Leishmania (Viannia) braziliensis or L. (Leishmania) amazonensis to investigate the role of IL-32 in infection." (PMID 28241012, 2017). "By contrast, IL-1Ra mRNA and IL-1Ra protein were decreased after infection with L. (L.)amazonensis and silencing of IL-32." (PMID 28241012, 2017). "The infection index with both Leishmania species (4 h; 24 h) was increased in IL-32 knockdown cells." (PMID 28241012, 2017). "Both IL-8 mRNA and IL-8 protein were strongly reduced after infection with either Leishmania species when IL-32 was silenced." (PMID 28241012, 2017). "Because silencing of IL-32 is a transitory process, we checked for IL-32 expression 48 h after infection." (PMID 28241012, 2017). "Cells depleted of IL-32 exhibited an increase in macrophage infection index after Leishmania species infection, which was reversed when IL-32γ was overexpressed." (PMID 28241012, 2017). "To determine the role of NOD2 in leprosy infection, we silenced NOD2 gene expression in human monocytes using short interfering RNAs (siRNAs) and measured the induction of IL-32 mRNA in response to infection with live M. leprae." (PMID 27297389, 2016). "Here, we demonstrate that infection of monocytes with M. leprae induces the NOD2-dependent production of IL-32 as well as DC differentiation." (PMID 27297389, 2016). "Infection of human macrophages THP-1 or PBMCs (peripheral blood mononuclear cells) with MTB H37Rv induce IL-32 expression." (PMID 27634911, 2016). "We investigated the effect of MDP structure on the innate immune response, finding that infection of monocytes with M. leprae induces IL-32 and DC differentiation in a NOD2-dependent manner." (PMID 27297389, 2016). "The expanding knowledge of IL-32 indicates that it plays a vital role in inflammation or infection with various pathogens." (PMID 26087456, 2015). "Although CagA- strain infection slightly increased the expression of IL-32 in AGS cells, the induction of IL-32 mRNA and protein level by CagA- strain infection was significantly lower than that by H. pylori 11637 strain infection." (PMID 24633341, 2014). "In keratinocytes and other epithelial cells, in vitro or in vivo, during infections or inflammatory diseases IL-32 is produced." (PMID 24884781, 2014). "Among other genes found to display high, and significant expressional levels during infection were IL-1α, IL-32, growth differentiation factor 15 (GDF15) and, chemokine (C-C motif) ligand 22 (CCL22)." (PMID 23646188, 2013). "IL-32 has been proposed to play an important role in modulating innate and adaptive responses to infection." (PMID 21649914, 2011). "We found that PGE2 release in A549 cell culture supernatants stimulated by IV infection was increased and IL-32 production decreased by knocking down IL-32." (PMID 18414668, 2008). "Comparing the IV infection induced IL-32 level in cell culture with that in human individuals, a significant difference between them was observed, over 10-fold increase in cell culture versus 58.2% in human individuals." (PMID 18414668, 2008). "Further studies are needed to elucidate the mechanisms regulating IL-32 expression in severe infections and to determine whether this reduction has clinical significance." (PMID 40149726, 2025). "Our data suggest that the effects of IL-32 in T. cruzi infection could be even more pronounced if the parasite did not reduce the production of this cytokine at the beginning of the infection." (PMID 35097133, 2022). "Only infection with L2 stimulated production of GM-CSF, IL-1β, IL-6, IL-32, and CXCL12." (PMID 32039039, 2019).
infection (continued). "Indeed IL-32 silencing was reversed at this time, potentially explaining the results at this time point of infection." (PMID 28241012, 2017). "Next we investigated the cellular distribution of IL-32 after Leishmania species infection." (PMID 28241012, 2017). "In addition, it was observed that IL-32 and IL-6 are up-regulated by aberrant epigenetic modification during IV infection." (PMID 26490959, 2015). "Microbicidal mechanisms can be induced by IL-32 during these infections." (PMID 24884781, 2014). "Besides the role of IL-32 in chronic inflammatory diseases it has been demonstrated that this cytokine can be induced during infections and plays a role in immune response against pathogens." (PMID 24884781, 2014). "IL-32 protein levels decreased in subsequent hours post infection and could only be detected in a small quantity by western blot at 96 hpi." (PMID 23402302, 2013). "It has been reported that the IL-32 expression could be induced during infections of influenza A virus, HBV, HCV, HPV and HIV." (PMID 23402302, 2013). "IL-32 protein expression reached a peak value at 6 hours post infection (hpi)." (PMID 23402302, 2013). "IL-32 protein levels decreased with subsequent hours post infection." (PMID 23402302, 2013). "In the absence of infection, CF-TG cells constitutively exhibited an inflammatory signature, including genes that encode molecules such as IL-1α, IL-β, IL-32, TNFSF14, LIF, CXCL1 and PLAU." (PMID 19399182, 2009). "Little is known about IL-32 production by exogenous pathogens infection in human individuals." (PMID 18414668, 2008). "The effect of IL-32 on the regulation of IV infection induced PGE2 production was also determined." (PMID 18414668, 2008). "Future studies should investigate the presence of other IL-32 isoforms, in vivo, during microbial infection and attempt to identify IL-32 receptors to unravel the mechanisms through which IL-32 modulates immune responses during infection with different Leishmania species." (PMID 35309341, 2022). "In the present study, we have shown that the expression of IL-32 isoforms is dependent on duration of exposure to Leishmania antigens, which might reflect the ability of the parasite to modulate IL-32γ splicing as the infection progress." (PMID 32023240, 2020). "Considering that IL-32 expression is increased during the infection with various viruses, the up-regulation of IL-32 might be a promising therapeutic strategy, and the identification of the specific biological function of each IL-32 isoform would be of great importance in this endeavor." (PMID 26087456, 2015). "IL-32 has several roles including inducing the expression of inflammatory cytokines and adhesion molecules in T-lymphocytes, monocytes, macrophages, and epithelial cells and promoting monocyte differentiation into macrophages, which alters the responses of inflammatory cells against infection." (PMID 22413812, 2012). "Although HCMV can induce IL-3 secretion during early infection of MRC-5 cells, it has been observed that during prolonged infection, IL-32 transcript as well as protein levels were decreased with increasing miR-UL112-1 expression." (PMID 37896804, 2023). "Regarding inflammatory response, ChP organoids showed an increase in inflammatory cytokines CCL7, interleukin-32 (IL-32), CCL2, MCP1, IL-18, and IL-8 upon infection." (PMID 35337041, 2022). "In fact, in infection with influenza A, COX-2 triggers IL-32 production, and high IL-32 levels conversely inhibit COX-2 function." (PMID 34712431, 2021). "The regulation of IL-32 in human gastric epithelia cell line AGS was investigated by different cytokine stimulation and different H. pylori strain infection." (PMID 24633341, 2014). "The expression levels of IL-32 and hcmv-miR-UL112-1 in HCMV infected MRC-5 cells were detected at different stages of infection and time points." (PMID 23402302, 2013).
infection (continued). "Two viral components, the NS1 and viral replicative intermediate dsRNA were identified to be involved in IV infection triggered COX-2 and IL-32 expression in A549 cells." (PMID 18414668, 2008). "Notably, IL-32 expression is significantly higher during both the acute and AIDS stages of infection compared to the asymptomatic stage, implicating a possible immunosuppressive function." (PMID 41383621, 2025). "Patients with bloodstream bacterial infections, SARS-CoV-2 infections, or no documented infection had comparable IL-32 levels." (PMID 40149726, 2025). "Lastly, exclusive expression of many genes encoding immune mediators, which allocate to signaling by interleukins or chemokines could be detected in male-derived macrophages upon infection at 6 hpi, such as CXCL1, IL32, CCL7 and IL1B." (PMID 40794782, 2025). "We report a strong induction of numerous pro-inflammatory cytokines, chemokines and AMPs such as CXCL1, CXCL2, CXCL5, CXCL8, CCL20, TNFα, TSLP, IL-23α, IL-32, IL-6, hBD2 and S100A7 during the infection of monolayered primary keratinocytes and reconstructed epidermis with the wild-type PAK strain." (PMID 30070169, 2018). "IL-32 plays protective roles in multiple infectious diseases, such as HIV, influenza, cytomegalovirus, HBV, Leishmania braziliensis, Mycobacterium avium, and M. tuberculosis infection." (PMID 30426023, 2018). "Remarkably, the infection index was augmented in the absence of IL-32 and decreased in cells overexpressing this cytokine." (PMID 28241012, 2017). "In our hands, no specific IL-32 cell localization was detected in THP-1-derived macrophages during Leishmania species infection and it is not localized to parasite vacuoles in order to exert its biological functions." (PMID 28241012, 2017). "Semi-quantitative RT-PCR analysis revealed that IL-32 mRNA expression was significantly activated at IE stage but not at E or late (L) stages post-infection." (PMID 23402302, 2013). "No accumulation of either IL-32 mRNA or protein was found following the prolongation of HCMV-infection process." (PMID 23402302, 2013). "MRNA levels of genes encoding for chemokines (CXCL1 and CXCL5), cytokines (IL-10, IL-15 and IL-32), pattern recognition receptors (TLR1) and innate signaling molecules like IRAK3 and TRAF6, were all increased after MVA-C infection in comparison with MVA-WT-infected cells." (PMID 22536391, 2012). "In addition, we did not observe effects of infection on IL-32 levels in the spleen of IL-32γTg mice at any time evaluated." (PMID 35097133, 2022). "Together, these data indicate that microorganisms can induce IL-32 expression in immune and nonimmune cells to control the infection, but alternatively this cytokine might play a role in the pathogenesis of the diseases." (PMID 24884781, 2014).
cardiovascular diseases (13 papers, 2017 to 2026). "This study reveals that circulating IL32 levels are associated with impaired blood pressure control in individuals at risk of cardiovascular disease." (PMID 37108628, 2023). "IL-32 is a pro-inflammatory cytokine that promotes endothelial cell angiogenesis and modulates lipid metabolism, linking it to cardiovascular disease." (PMID 40149726, 2025). "This review discusses the current understanding of the role of these recently identified interleukins, such as IL-27, IL-31, IL-32, IL-33, and the IL-28 group (IL-28A, IL-28B, IL-29), in the development of cardiovascular diseases." (PMID 39844544, 2025). "IL-32 is also emerging as a strong contributor to cardiovascular disease, especially in chronically HIV-infected individuals." (PMID 41383621, 2025). "In humans, caproic acid is an anti-IL32 and anti-inflammatory player that has recently been shown to be correlated with cardiovascular diseases." (PMID 37420234, 2023). "IL-32 and IL-34 have recently been identified to play a role in specific patient populations with cardiovascular disease." (PMID 36769623, 2023). "Our results therefore lead to an area of research in which the effects of IL-32 and the promoter SNP in RA have to be studied relevant to response to treatment and cardiovascular diseases within these patients." (PMID 30232372, 2018). "This review summarizes the biological characteristics of IL-32 and its role in cardiovascular diseases, explores its involvement in inflammatory responses and other pathological processes, and evaluates its potential as both a biomarker and a therapeutic target." (PMID 42099604, 2026). "IL-32 has a central pathological role in HIV-related cardiovascular disease." (PMID 41383621, 2025). "Therefore, we suggest that the exploration of the role of IL-32 in RA should be continued in future research, focussing more specifically on treatment response, inflammation induced cardiovascular disease burden and cholesterol metabolism abnormalities." (PMID 30232372, 2018). "However, IL-32, especially the most extensively studied IL-32γ, has a Pandora’s box of roles in HIV infection, as it drives antiviral immunity, impairs the antiviral immune control, and mediates HIV-related cardiovascular diseases." (PMID 41383621, 2025).